MMP14 (matrix metallopeptidase 14)
Diseases named in the same sentence as MMP14 in open-access papers (continued):
Sharing a sentence is not in itself a finding about the gene and the disease.
hepatocellular carcinoma (42 papers, 2009 to 2025). A malignant tumor that arises from hepatocytes. "Researchers have reported that miR‐150‐5p hinders the motility of hepatoma cell motility via MMP‐14 regulation." (PMID 39466654, 2024). "miR-150-5p has been identified to target matrix metalloproteinase 14 (MMP14) and downregulated its expression in hepatoma cells." (PMID 36112264, 2023). "A possible role of MMP14 rs1042703 as a biomarker in hepatocellular carcinoma (HCC) was investigated in a Taiwanese study with rs1042703 CC genotype resulting in lower MMP14 expression and lower risk of acquiring HCC." (PMID 29138529, 2017). "MiR-150-5p, located on chromosome 19q13, was shown to be downregulated in hepatocellular carcinoma tissues, and may suppress the progression of hepatocellular carcinoma by inhibition of the migration of hepatoma cell by targeting MMP14 (matrix metallopeptidase 14)." (PMID 28099946, 2017). "But in hepatocellular carcinoma ZFAS1 serves as an oncogene and promotes cancer metastasis by regulating the expression of related genes such as MMP14 and MMP16." (PMID 32760219, 2020). "For instance, lncRNA ZFAS1 activated the expression of ZEB1, MMP-14 and MMP-16 to promote tumor growth and metastasis by sponging miR-150 in hepatocellular carcinoma." (PMID 31827393, 2019). "In a hepatocellular carcinoma cell line expressing high endogenous levels of PROX1, its silencing increased both MMP14 expression and MMP14-dependent invasion in 3D." (PMID 29934628, 2018). "In hepatocellular carcinoma, ZFAS1 functions as an oncogene in HCC progression by binding miR-150, which adsorbs ZEB1, MMP14 and MMP16 expression, and abrogating the tumor-suppressive." (PMID 29262629, 2017). "ZFAS1 was reported to promote hepatocellular carcinoma metastasis via sponging miR-150 to activate ZEB1, MMP14, and MMP16." (PMID 28983240, 2017). "The mRNA levels of both MMP-2 and MMP-14 in human hepatocellular carcinoma (HCC) cell SMMC-7721 were up-regulated by Cu2+ in a concentration dependent manner, whereas the mRNA levels for other tested MMPs (MMP-1, MMP-3 and MMP-9) were not changed when treated with up to 40 μM Cu2+." (PMID 28881637, 2017). "According to the expression levels of GRP78, MMP-2, MMP-9, MMP-14 and TIMP-1 in hepatocellular carcinoma cell lines SMMC7721 and hepG2, we used SMMC7721 as the in vitro invasion model for further functional analysis." (PMID 22546345, 2012). "Based on the expression status of GRP78, MMP-2, MMP-9, MMP-14 and TIMP-2 in hepatocellular carcinoma cell lines SMMC7721 and HepG2, we choose SMMC7721 to establish the in vitro invasion model for further research." (PMID 22546345, 2012). "We choose hepatocellular carcinoma cell line SMMC7721 for the establishment of in vitro invasion and metastasis model according to the expression levels of GRP78, MMP-2, MMP-9, MMP-14 and TIMP-2." (PMID 22546345, 2012). "Furthermore, In hepatocellular carcinoma, CXCL10/TLR4-mediated MMP14 activation promotes recruitment of monocytic myeloid-derived suppressor cells (MDSCs) after acute liver injury, fueling post-transplant HCC relapse, as evidenced by clinical data, animal studies, and cell-culture assays." (PMID 41404065, 2025). "The role of virus proteins on tumor invasiveness was first noted in a study demonstrating in hepatoma cell line the ability of hepatitis B virus (HBV) X protein to induce expression of matrix metalloproteinases MMP-2 and MT1-MMP (MMP-14), via a Cox 2-dependent mechanism." (PMID 23967226, 2013). "In addition, we noted the different expression profiles of miR-337-3p in publicly available clinical tumor datasets, and found that miR-337-3p attenuated the MMP-14 expression in cervical cancer cells, but not in hepatocellular cancer, prostate cancer, or renal cell carcinoma cells." (PMID 26084291, 2015).
prostate carcinoma (37 papers, 2008 to 2025). A carcinoma that arises from epithelial cells of the prostate gland. "This included 2 matrix metallopeptidases, MMP1 and MMP14, both of which are overexpressed in human prostate tumors and promote invasion and metastasis of prostate cancer cells." (PMID 37870957, 2023). "Recently, the involvement of MMP14 was also indicated in epithelial-to-mesenchymal transition in squamous cell carcinoma and prostate cancer alike." (PMID 32575583, 2020). "LAMA5 has also been reported to be cleaved by membrane-type 1 MMP (MMP14), a transmembrane protease that can promote the cell migration of prostate cancer cells via cleavage of LAMA5 in laminin-1047." (PMID 27324842, 2016). "The GC-rich region within human MMP-14 promoter serves as the putative binding site for transcription factor Sp1 in fibrosarcoma and prostate cancer cells." (PMID 23394613, 2013). "Namely, the AR, in interaction with ITGB1 and membrane type-matrix metalloproteinase 1 (MT-MMP-1 or MMP14), activates a protease cascade triggering ECM remodeling, which facilitates the cancer-associated fibroblast invasion through the ECM and a subsequent interaction with prostate cancer cells." (PMID 38255186, 2023). "Consistent with previous research, our RT-qPCR results demonstrated that SChLAP1 knockdown significantly inhibited the expression of invasion markers MMP-9 and MMP-14, as well as the proliferation marker VEGF, in prostate cancer cells." (PMID 39975023, 2025). "In correlation, increased levels of MMP14 were detected in prostate cancer cells, and active MMP2 was found to be inversely correlated with the disease-free survival time in prostate cancer patients." (PMID 32575583, 2020). "In prostate cancer cells, ECM-deposited latent TGFβ can be activated by membrane type I-matrix metalloprotease (MT1-MMP/MMP14), which then induces the secretion of Wnt5a; the sequential action of TGFβ and Wnt5a sustain EMT and invasiveness of the tumor cells." (PMID 30463358, 2018). "Several ways to induce EMT in prostate cancer cells have been described, including overexpression of CAV1 and ID1 or MMP14 in LNCaP cells, EGF treatment of DU145 cells, depletion of PDEF or BMP7 treatment of PC3 cells." (PMID 18852876, 2008). "Moreover, it has also been shown that PMPs can stimulate MMP-2 activation and secretion, MMP-14 expression or MMP-dependent cell migration in lung, breast and prostate cancer." (PMID 36882818, 2023). "The membrane type I-matrix metalloprotease (MT1-MMP or MMP14) promotes EMT and invasiveness by activating extracellular TGFβ, which then induces the secretion of Wnt5a and thus provides a paracrine signal to epithelial prostate cancer cells." (PMID 27367735, 2016). "In the present study, we demonstrated that MMP-2, MMP-9 and MMP-14 are positive in prostate cancer and its regulators are negative in the majority of cases." (PMID 26742965, 2015).
fibrosarcoma (33 papers, 2004 to 2024). A malignant mesenchymal fibroblastic neoplasm affecting the soft tissue and bone. "Specifically, it inhibits MMP-1, MMP-3, MMP-7, MMP-9, and MMP-14, which hinders the expansion of HUVECs and the activated process of proMMP-2 regulated by MMP-14 in human fibrosarcoma cells." (PMID 38611849, 2024). "Altogether, these results indicate that, as in various carcinoma and in fibrosarcoma cells, MMP14 activity is essential for the proliferation and aggressive growth pattern of uLMS cells in collagen‐rich environments." (PMID 37078535, 2024). "MiR-181a-5p was downregulated in aggressive human breast cancer, fibrosarcoma, and colon cancer, where the MMP-14 is upregulated." (PMID 35626707, 2022). "Interestingly, EDPs increased the levels of MMP‐14 at the cell surface of MDA‐MB‐231 cells, while engagement of MMP‐14 following EDP treatment had only been evidenced for fibrosarcoma 36 and endothelial cells." (PMID 30186741, 2018). "MMP-14 is a direct target gene of miR-181a-5p; essentially, miR-181a-5p-mediated reduction of MMP-14 was sufficient to reduce in vivo angiogenesis in chick chorioallantoic membrane assays and impair new blood vessel formation induced by HT1080 (a human fibrosarcoma cell line)." (PMID 35626707, 2022). "With a highly potent invasive potential, the fibrosarcoma HT1080 cells exhibit aberrant secretion of MMP-2 and MMP-14, which acts as the receptor of TIMP2; accordingly, this may be the mechanistic basis for selective intense binding of the TIMP2-based protein LT to fibrosarcomas." (PMID 29250984, 2018). "Similarly, the non-constitutive, furin-independent processing of proMMP14 was also reported to occur in fibrosarcoma HT-1080 and CCL-137 normal fibroblast cells, where the 63 kDa proform of MMP14 was detected in both, the tumor-derived cell line and in normal cells upon PMA stimulation." (PMID 32575583, 2020).
colorectal cancer (32 papers, 2000 to 2025). A primary or metastatic malignant neoplasm that affects the colon or rectum. "Tumour‐associated macrophages M2 expressing MMP14 are involved in complicated matrix remodelling, as demonstrated in a colorectal cancer orthotopic mouse model." (PMID 35150061, 2022). "Matrix metalloproteinase 14 (MMP14) expression is implicated in progression of colorectal cancer, but its role in the tumor microenvironment (TME) has been unclear." (PMID 36052235, 2022). "Our results suggest a novel risk stratification of stage III colorectal cancer based on MMP14 expression in CAFs." (PMID 36052235, 2022). "A previous preclinical study suggested that MMP14 is associated with resistance to 5-FU treatment in colorectal cancer." (PMID 36052235, 2022). "According to the multivariate Cox regression analyses, Hes1 (HR, 2.41; 95% CI, 1.07 to 5.43) and MMP14 (HR, 2.36; 95% CI, 1.02 to 5.46) remained positively associated with deaths from colorectal cancer." (PMID 26650241, 2015). "We hypothesized that MMP14 may be associated with immune cell infiltration in colorectal cancer due to its significant role in the tumor microenvironment." (PMID 40352589, 2025). "Given that CAFs were defined as αSMA-positive cells in our mIHC analysis, the association of MMP14+ CAFs with colorectal cancer progression might be explained by production of the active form of TGF-β mediated by the proteolytic activity of MMP14." (PMID 36052235, 2022). "In addition, a study based on data in The Cancer Genome Atlas (TCGA) found that a high MMP14 expression level was associated with poor prognosis in stage I–III colorectal cancer." (PMID 36052235, 2022). "Studies have reported that high MMP14 expression is associated with poor prognosis and might serve as a marker of progression in muscle-invasive bladder cancer and colorectal cancer." (PMID 34587931, 2021). "To further elucidate the relationship between high MMP14 gene expression and colorectal cancer, we utilized single-cell transcriptome data from public databases for analysis." (PMID 40352589, 2025). "Hes1 overexpression elevates STAT3 phosphorylation levels, upregulates MMP14 expression via the Hes1-STAT3-MMP14 cascade, and potentiates invasiveness in colorectal cancer." (PMID 40755759, 2025). "Recent research has underscored the importance of MMP14‐expressing CAF in the progression of stage III colorectal cancer (CRC), indicating their potential as a therapeutic target for CRC treatment." (PMID 40226936, 2025). "Based on existing literature on colorectal cancer, we selected MMP14 as the final candidate gene for subsequent studies." (PMID 40352589, 2025). "We employed univariate Cox regression analysis to identify 18 prognostic genes and evaluate their clinical significance in relation to MMP14 co-expression in colorectal cancer." (PMID 40352589, 2025). "Finally, several matrix metalloproteinases (Mmp14, Mmp15, Mmp19), which are linked to poor prognosis of liver or colorectal cancer patients, are also upregulated by P2-HNF4α and dysregulation of genes involved in drug metabolism could impact treatment of liver cancer." (PMID 38111711, 2023). "The relevance of MMP14 to colorectal cancer progression was explored by analysis of transcriptomic data for colorectal adenocarcinoma patients (n = 592) in The Cancer Genome Atlas." (PMID 36052235, 2022). "We therefore divided our stage III colorectal cancer patients into four groups according to these two independent biomarkers (IS-Immunoscore and MMP14+ CAF/CAF ratio)." (PMID 36052235, 2022). "Further research is therefore needed to determine how MMP14 contributes to colorectal cancer progression through regulation of M2-TAM activity." (PMID 36052235, 2022). "Further studies are warranted to develop new treatment strategies related to the role of MMP14+ CAFs in the progression of colorectal cancer." (PMID 36052235, 2022).
colorectal cancer (continued). "Our study now suggests that CAFs are a key player in postoperative recurrence of stage III colorectal cancer as a result of their expression of MMP14." (PMID 36052235, 2022). "We therefore propose a new and improved stratification of stage III colorectal cancer based on both MMP14+ CAFs and the Immunoscore." (PMID 36052235, 2022). "To explore the clinical relevance of MMP14 in colorectal cancer, we first analyzed publicly available gene expression data for tumor tissue of the colorectal adenocarcinoma data set in TCGA." (PMID 36052235, 2022). "Matrix metalloproteinase 14 (MMP14) is a transmembrane proteolytic enzyme that plays a key role in establishment of a desmoplastic TME in colorectal cancer." (PMID 36052235, 2022). "We next investigated further the relation between TAMs and MMP14+ CAFs in stage III colorectal cancer suggested by our analysis of TCGA transcriptomic data." (PMID 36052235, 2022). "We performed 12-color multiplex immunohistochemistry (mIHC) to evaluate the relation of MMP14 protein expression in multiple cell subsets including intratumoral immune cells to colorectal cancer progression." (PMID 36052235, 2022). "Overall, these results suggested that MMP14 expression, in association with CAFs and M2-TAM infiltration into tumor tissue, contributes to poor survival outcome in patients with colorectal cancer." (PMID 36052235, 2022). "A recent study revealed that MMP14 is a biomarker of poor prognosis in patients with colorectal cancer." (PMID 32986377, 2020). "Therefore, MMP14 can serve as a biomarker for predicting the prognosis of colorectal cancer patients." (PMID 40352589, 2025). "We found that CAFs are an important source of MMP14 and that MMP14+ CAFs may act in collaboration with TAMs to promote the progression of colorectal cancer." (PMID 36052235, 2022). "We have now conducted a retrospective biomarker analysis of surgically resected tumor specimens from patients with stage III colorectal cancer attending Kindai University Hospital as well as an analysis of TCGA transcriptomic data in order to clarify this role of MMP14." (PMID 36052235, 2022). "Collectively, our spatial profiling data thus suggested that intratumoral CAFs might contribute to tumor progression in stage III colorectal cancer by expressing MMP14." (PMID 36052235, 2022). "Our results suggest that MMP14+ CAFs play an important role in progression of stage III colorectal cancer and may therefore be a promising therapeutic target." (PMID 36052235, 2022). "The role of MMP14 in the TME was investigated in a retrospective analysis of tumor samples from 86 individuals with stage III colorectal cancer by single cell–based spatial profiling of MMP14 expression as performed by 12-color multiplex immunohistochemistry (mIHC)." (PMID 36052235, 2022). "MMP14 plays an important role in the progression and prognosis of colorectal cancer and may be a useful biomarker for predicting survival after colectomy." (PMID 34604053, 2021). "To examine further how MMP14 expression in tumors might contribute to poor survival outcome in colorectal cancer, we performed 12-color mIHC analysis of tumor tissue surgically removed from patients with stage III colorectal cancer at Kindai University Hospital." (PMID 36052235, 2022). "We here showed that MMP14 expression in CAFs was associated with the infiltration of M2-TAMs into the TN, suggesting that such expression may be a determinant of intratumoral M2-TAM activity in stage III colorectal cancer." (PMID 36052235, 2022). "These various observations suggest that MMP14 expression in tumors may contribute to the recurrence of colorectal cancer in a manner dependent on the TME, and that clarification of this role of MMP14 may lead to improvement in the survival of individuals with stage III colorectal cancer." (PMID 36052235, 2022).
colorectal cancer (continued). "In summary, our study has suggested that MMP14+ CAFs play an important role in tumor progression and are therefore a potential therapeutic target in stage III colorectal cancer." (PMID 36052235, 2022). "Further evidence revealed that miR-10a-5p targets matrix metallopeptidase 14 (MMP14) and actin gamma 1 (ACTG1), both of which positively regulate BCL-2 levels and render cancer cells resistant to anoikis in colorectal cancer cells." (PMID 33435156, 2021). "This study implied that MMP11, MMP14, MMP17, and MMP19 are potential targets of precision therapy for patients with colorectal cancer." (PMID 34804973, 2021). "lncRNA TUG1 promoted the proliferation and migration of colorectal cancer cells through the miR-145-5p/TRPC6 pathway, EMT pathway, miR-26a-5p/MMP14/p38MAPK/Hsp27 axis, Twist1/EMT signal pathway, or by overexpression." (PMID 34039257, 2021). "Specifically, an elevated level of MMP-14 was observed in a sensitive colorectal cancer cell line, whereas no significant changes were noted in the resistant cell line." (PMID 39199626, 2024). "Together, these results suggested that MMP14-related colorectal cancer aggressiveness might be explained, at least in part, by the promotion of M2-TAM infiltration into the TN by MMP14+ CAFs." (PMID 36052235, 2022). "Also, MMP11, MMP14, MMP17, and MMP19 are potential targets of precision therapy for patients with colorectal cancer." (PMID 34804973, 2021).